GDE1 (glycerophosphodiester phosphodiesterase 1)
Description:
Hydrolyzes the phosphodiester bond of glycerophosphodiesters such as glycerophosphoinositol (GroPIns) and glycerophosphoethanolamine (GroPEth), to yield a glycerol phosphate and an alcohol (By similarity). Hydrolyzes glycerophospho-N-acylethanolamines to N-acylethanolamines in the brain and participates in bioactive N-acylethanolamine biosynthesis such as anandamide (an endocannabinoid), N-palmitoylethanolamine (an anti-inflammatory), and N-oleoylethanolamine (an anorexic). In addition, has a lysophospholipase D activity by hydrolyzing N-acyl-lysoplasmenylethanolamine (N-acyl-lysoPlsEt) to N-acylethanolamine. However lysophospholipase D activity is lower than glycerophosphodiester phosphodiesterase activity (By similarity). Has little or no activity towards glycerophosphocholine (By similarity).
Synonyms: MIR16; 363E6.2
Tractability: Antibody: its Gene Ontology location is reachable by antibodies, with high confidence; UniProt places it where antibodies can reach, with medium confidence; UniProt predicts a signal peptide or a membrane-spanning region; the Human Protein Atlas places it where antibodies can reach. PROTAC: ubiquitination databases record sites on it; its protein half-life has been measured.
Gene: Protein-coding gene on chromosome 16 (19,501,693 to 19,522,123, reverse strand). Ensembl gene ENSG00000006007.
Subcellular location: Cell membrane; Cytoplasmic vesicle membrane
Subcellular location (Human Protein Atlas): Vesicles; Nucleoplasm; Plasma membrane
Pathways (Reactome):
Metabolism: Glycerophospholipid catabolism
Gene Ontology:
Molecular function: protein binding; glycerophosphodiester phosphodiesterase activity; glycerophosphoinositol glycerophosphodiesterase activity; phosphatidylcholine lysophospholipase activity; phosphoric diester hydrolase activity
Biological process: ethanolamine metabolic process; glycerophospholipid catabolic process; lipid metabolic process; N-acylethanolamine metabolic process; phospholipid metabolic process
Cellular component: cytoplasmic vesicle membrane; membrane; plasma membrane
Genetic constraint (gnomAD): Loss-of-function variants: 9 observed, 9.82 expected, observed/expected ratio (o/e) 0.92, 90% interval 0.55 to 1.58. That is too few expected variants to judge how well the gene tolerates losing a copy. Missense variants: 194 observed, 202.18 expected, observed/expected ratio (o/e) 0.96, 90% interval 0.85 to 1.08. Synonymous variants: 97 observed, 85.41 expected, observed/expected ratio (o/e) 1.14, 90% interval 0.96 to 1.34.
Homologues: Orthologues: chimpanzee GDE1 (99% identical), macaque GDE1 (99% identical), dog GDE1 (92% identical), guinea pig GDE1 (91% identical), rabbit GDE1 (90% identical), pig GDE1 (89% identical), rat Gde1 (88% identical), mouse Gde1 (87% identical), tropical clawed frog gde1 (66% identical), zebrafish gde1 (57% identical), Caenorhabditis elegans T22G5.1 (27% identical), Caenorhabditis elegans ZC155.4 (27% identical). Paralogues in human: GDPD1 (20% identical), GDPD2 (20% identical), GDPD4 (19% identical), GDPD5 (18% identical), GDPD3 (16% identical).
Diseases named in the same sentence as GDE1 in open-access papers:
GDE1 is named in the same sentence as 12 diseases in open-access papers, as found by Europe PMC text mining. Sharing a sentence is not in itself a finding about the gene and the disease. The quoted sentences say what the papers report.
colon adenocarcinoma (2 papers, 2020 to 2022). "In Shen’s transcriptomics analysis of colon adenocarcinoma, the expression of GDE1 is significantly lower than that of normal tissues, indicating abnormal Cho metabolism in malignant tissues." (PMID 35168606, 2022). "Taken together, our study showed that GDE1 exhibits considerable potential as a novel therapeutic target for non-mucin-producing colon adenocarcinoma." (PMID 32095326, 2020).
bladder cancer (1 paper, 2020). "To better understand the role of ECs and NAEs in bladder cancer, we analyzed gene expression data from TGCA database regarding the metabolic pathway of the ECS, comprising the synthetic enzymes (PLCB1-4, PTPN22, ABHD4, GDE1, DAGLA, DAGLB, and NAPE-PLD) and the hydrolytic ones (FAAH, NAAA, and MGLL)." (PMID 32260109, 2020).
cardiac hypertrophy (1 paper, 2019). "Additionally, Gde1, which is involved in skeletal muscle development, Pdlim5, a promoter of cardiac hypertrophy, and Ppp1cb, a regulator of cell division, glycogen metabolism, and muscle contractility, were overexpressed." (PMID 31480808, 2019).
Hepatic steatosis (1 paper, 2015). Steatosis is a term used to denote lipid accumulation within hepatocytes. "Several lines of evidence indicate that Gde1 is a causal gene for hepatic steatosis in the chromosome 7 locus." (PMID 26067236, 2015). "Furthermore, by integrating transcriptomic information for the liver and adipose tissue, we identified two high-confidence candidate genes (Gde1 and Knop1) for hepatic steatosis on chromosome 7." (PMID 26067236, 2015). "Utilizing transcriptomic data from the liver and adipose tissue, we identified several high-confidence candidate genes for hepatic steatosis, including Gde1, a glycerophosphodiester phosphodiesterase not previously implicated in triglyceride metabolism." (PMID 26067236, 2015).
ovarian carcinoma (1 paper, 2022). A malignant neoplasm originating from the surface ovarian epithelium. "GDE1 expression is significantly reduced in drug-resistant ovarian cancer samples." (PMID 35968507, 2022).
steatosis (1 paper, 2015). Increased lipid within the cytoplasm of cells. "The finding of positive correlation between hepatic Gde1 expression and steatosis suggests that increased expression of Gde1 would promote hepatic TG accumulation." (PMID 26067236, 2015).
tumor (3 papers, 2020 to 2022). "In this study, we provide the first piece of evidence to show that GDE1 is an important tumor suppressor gene through the function of its metabolite inositol." (PMID 32095326, 2020).
cancer (2 papers, 2020 to 2021). A tumor composed of atypical neoplastic, often pleomorphic cells that invade other tissues. "Taken together, these studies show that inositol, as an enzymatic product of GDE1, plays a key role in anti-cancer." (PMID 32095326, 2020). "Contra to the attention paid to the anti-cancer effects of inositol, little is known about the connection between GDE1 and cancer." (PMID 32095326, 2020). "Taken together, our results showed that GDE1 was specially associated with N-COAD subtype prognosis, suggesting that it could be a potential novel cancer target for N-COAD." (PMID 32095326, 2020). "Our results suggest that GDE1 may be a cancer suppressor by up-regulating the inositol metabolism pathway." (PMID 32095326, 2020).
GDE1 also shares sentences with these, for which no sentence is quoted: breast tumor (1 paper); Glucose intolerance (1); myelodysplastic syndrome (1); Obesity (1).